MIR483 (microRNA 483)
Synonyms: hsa-mir-483; MIRN483; mir-483
Gene: MicroRNA gene on chromosome 11 (2,134,134 to 2,134,209, reverse strand). Ensembl gene ENSG00000207805.
Diseases named in the same sentence as MIR483 in open-access papers:
MIR483 is named in the same sentence as 2 diseases in open-access papers, as found by Europe PMC text mining. Sharing a sentence is not in itself a finding about the gene and the disease. The quoted sentences say what the papers report.
cancer (2 papers, 2024). A tumor composed of atypical neoplastic, often pleomorphic cells that invade other tissues. "Despite the highlighted differences between mouse and human Igf2/Mir483 regulation, our work has potential relevance to human imprinting syndromes, cancer, and genomic imprinting in general." (PMID 39283743, 2024). "Functionally, both MIR483 and MIR663A have been shown to suppress apoptosis in cancer cells, and this might also be related to the phenotype observed in our study." (PMID 38886809, 2024).
MIR483 also shares sentences with these, for which no sentence is quoted: Ewing sarcoma (1 paper).